TLR2 (toll like receptor 2)
Diseases named in the same sentence as TLR2 in open-access papers (continued):
Sharing a sentence is not in itself a finding about the gene and the disease.
cholesteatoma (8 papers, 2014 to 2021). A pathologic process characterized by the proliferation of keratinizing squamous epithelium resulting in the accumulation of keratin and cells in the middle ear and/or mastoid. "Among all TLRs that we tested,TLR4 was the most abundantly expressed in acquired cholesteatoma, followed by TLR2." (PMID 26639190, 2015). "To exclude the involvement of TLR2,we established a TLR2−/− mouse model of acquired cholesteatomato investigate the roll of TLR2 in acquired cholesteatoma." (PMID 26639190, 2015). "In addition, a comparison of TLR2 expression in normal canal skin, COM, and cholesteatoma showed higher TLR2 mRNA and protein levels in COM and cholesteatoma mucosa and granulation tissue than in normal external auditory canal skin." (PMID 34360632, 2021). "Although an up-regulation of TLR2 was observable in cholesteatoma tissue, deficiency in TLR2 in mice did not affect disease severity or inflammatory responses." (PMID 31947538, 2020). "Using this method, we aimed to investigate whether the middle ear mucosa in ears with cholesteatoma has altered gene expression in relation to its control tissue by the examination of TLR2, TLR4 and c-MYC." (PMID 32915926, 2020). "A down-regulation of TLR4 was seen in middle ear mucosa from a group of patients with CMED, including cholesteatoma and an up-regelation of TLR2 and 4 in immunohistochemical analysis in tissue samples from five cholesteatoma patients, in comparison to normal mucosa, was detected respectively." (PMID 32915926, 2020). "In children, a higher expression was seen of TLR2 and 4 in cholesteatoma compared to skin." (PMID 32915926, 2020). "In adults TLR2 and 4 expression in cholesteatoma was higher expressed compared to healthy mucosa." (PMID 32915926, 2020). "Moreover, TLR2 deficiency did not relieve disease severity, inflammatory responses, or osteoclast formation.Therefore, the pathogenesis of acquired cholesteatoma may be dependent on TLR4 instead of TLR2." (PMID 26639190, 2015). "The occurrence of participants of the innate immunity, TLR2 and TLR4, were analysed in order to compare healthy middle ear mucosa to cholesteatoma." (PMID 32915926, 2020). "We used WT,TLR2−/−, and TLR4−/− mice to establish experimental models of cholesteatoma and evaluated the clinical features of these mice." (PMID 26639190, 2015). "We have reported that TLR2, TLR3, and TLR4 are expressed in epithelial cells, including human acquired cholesteatoma and cancer cells." (PMID 25385222, 2015). "However, other studies have obtained different results, reporting that TLR2 is weakly expressed in normal middle ear samples and is up-regulated in COM and cholesteatoma compared with normal middle ear samples." (PMID 34360632, 2021). "Previous studies have shown dysregulation of TLR2 and TLR4 within the cholesteatoma matrix itself." (PMID 32915926, 2020). "Among all the TLRs that we tested, TLR4 but not TLR2 was up-regulated and related to the disease severity of human acquired cholesteatoma.TLRs recognize numerous structurally defined but not necessarily structurally related ligands." (PMID 26639190, 2015). "From immunohistochemistry studies of biopsies from the normal ear canal and acquired cholesteatoma (an abnormal growth of keratinized squamous epithelium), it appears that expression of TLR2, TLR3 and TLR4 is detected and regulated as a function of cholesteatoma." (PMID 25161655, 2014). "We could not observe any clear dysregulation of TLR2 or TLR4 mRNA in the mucosa from patients with cholesteatoma." (PMID 32915926, 2020). "Microarray analysis showed significant upregulation for NOD2, not for NOD1, TLR2, or TLR4 in cholesteatoma." (PMID 25922834, 2015).
cryptococcal infection (8 papers, 2007 to 2023). "In this study, mice were immunized with heat-killed yeast of C. gattii associated with different doses of TLR2 agonist that should induce a predominant pro-inflammatory response, which is considered beneficial to combat cryptococcosis." (PMID 36743957, 2023). "The administration of synthetic TLR2 agonists can be relevant because of the induction of a pro-inflammatory immune response that is beneficial to combat cryptococcosis." (PMID 36743957, 2023). "The role of TLR2 during the protective immune response to cryptococcosis varies, as the response is dependent on strain and capsule variability." (PMID 29518906, 2018). "Therefore, the capacity of TLR2 agonists to modulate the adaptive and innate immune responses should be investigated in the development of immunotherapeutic strategies against cryptococcosis, which can impact Cryptococcus spp." (PMID 36743957, 2023). "Although various studies have been conducted to characterize the role of TLRs, the question still remains whether TLR2, TLR4, and heterodimers TLR1/2 and TLR2/6 are required for cryptococcal recognition and protective immune responses to cryptococcosis." (PMID 29518906, 2018). "The development and maintenance of Th1 and Th17 cells induced by TLR2 agonists should be evaluated as a mechanism to control cryptococcosis, although the immunomodulatory activity of TLR2 agonists in macrophages could be more relevant in combating cryptococcosis." (PMID 36743957, 2023). "Taken together, TLR2 and TLR4 signals, independently of their limited role in host response against cryptococcosis, are useful in the modulation of innate immune response over time during Cryptococcus spp." (PMID 33304649, 2020). "A third study of pulmonary cryptococcal infection found that TLR-2 was not important for resistance to infection, using colony counts and immunologic responses as criteria." (PMID 32545735, 2020). "In one study, MyD88 and TLR-2 appeared to play a role in resistance to pulmonary cryptococcal infection in mice, while TLR-4 did not." (PMID 32545735, 2020). "Other studies, however, found no major role for TLR2 in survival of cryptococcal infections in a murine model." (PMID 23383232, 2013). "More recently MyD88 and TLR2 but not TLR4 were shown to be required for host defense against Cryptococcus neoformans infection." (PMID 17982419, 2007). "TLR2−/− and TLR-4−/− mice infected with C. neoformans show normal pro-inflammatory cytokine responses and similar survival rates to their wild type counterparts, and there are no reports of cryptococcal infections associated with their deficiencies." (PMID 37998856, 2023). "While TLR2 and TLR4 can be activated by cryptococcal components, these receptors do not play major roles in the defense against cryptococcal infections." (PMID 37998856, 2023).
disseminated candidiasis (8 papers, 2016 to 2023). Systemic candidiasis occurs when Candida yeast enters the bloodstream and may spread (becoming disseminated candidiasis) to other organs, including the central nervous system, kidneys, liver, bones, muscles, joints, spleen, or eyes. "However, there are conflicting reports regarding the susceptibility of TLR2 knockout mice to disseminated candidiasis." (PMID 37872182, 2023). "A similar role of TLR2 was also observed in a murine model of disseminated candidiasis, where TLR2 exerts anti-inflammatory effect by promoting IL-10 production and Treg cell proliferation." (PMID 34912336, 2021). "Lack of TLR4 and TLR2 responses were shown to affect disseminated candidiasis in mice: lack of TLR4 caused an increased C. albicans kidney burden, while blocking of TLR2 inhibited the production of inflammatory cytokines such as tumor necrosis factor alpha (TNF-α) and IL-1β." (PMID 33526565, 2021). "Specifically, Toll Like Receptor 2 (TLR2) promotes Treg cell development during C. albicans infection, as evidenced by the reduction in Treg cells and lower levels of the immunoregulatory cytokine IL-10 observed in infected TLR2−/− mice that display increased resistance to disseminated candidiasis." (PMID 27973396, 2016).
E. coli infection (8 papers, 2015 to 2025). "In contrast to our findings, the TLR2 study revealed that TLR4-deficient mice were more susceptible to meningitic E. coli infection." (PMID 40821830, 2025). "Pretreatment with three different doses of L. plantarum 17–5 significantly reduced the expression of TLR2, TLR4 and MyD88 mRNA after E. coli infection (P < 0.05)." (PMID 35764986, 2022). "Live E. coli infection also upregulates expression of additional constituents of the innate responses, including CD14, TLR2 and PYCARD, proteins that recognize and orchestrate responses to bacterial infection." (PMID 26933871, 2016). "Similarly, meningitic E. coli infection significantly upregulates VEGFA expression, which in turn negatively regulates TJ protein expression to increase BBB permeability via the TLR2-MAPK-ERK1/2 pathway." (PMID 38233877, 2024). "The phagocytosis-promoting receptors were upregulated after E. coli infection, including complement receptor (CR1, CR3, and iC3b), integrins (αMβ2, αVβ3, and αVβ5), toll-like receptor (TLR2, TLR4, and TLR6), might accelerate the phagosome maturation." (PMID 36411420, 2023). "In addition, the blockade of TLR2 and TLR4 with the mAbs T2.5 and 1A6, respectively, prevented otherwise fatal shock in experimental Salmonella enterica or Escherichia coli infection models." (PMID 26147469, 2015).
Giardia infection (8 papers, 2017 to 2023). "Our findings are in line with previous reports that demonstrated increased cytokine production in TLR2-deficient mice which led to reduction in parasite burden and alleviated giardiasis." (PMID 33919165, 2021). "Mice deficient in TLR2 showed attenuation of giardiasis by increasing proinflammatory cytokine secretion, which was dependent on the AKT signaling pathway." (PMID 34238339, 2021). "Together, our results suggested that TLR2 deficiency leads to alleviation of giardiasis and reduction of parasite burden through the promotion of proinflammatory cytokines production." (PMID 28979269, 2017). "An elevated inflammatory response mediated by TLR2/MAPK signaling plays a role in giardiasis severity." (PMID 34943932, 2021). "The role of host TLR2 on giardiasis was explored in TLR2−/−, AKT-blocked (using MK-2206) and WT mice experimentally infected with G. lamblia cysts." (PMID 28979269, 2017). "To explore the role of TLR2 during G. lamblia infection in vivo, we developed a mouse model of persistent giardiasis using purified G. lamblia WB cysts." (PMID 28979269, 2017). "In this study, we found that Giardia infection led to a decreased parasite burden, short parasite persistence and an increased weight gain rate in infected TLR2−/− mice compared with in infected WT mice." (PMID 28979269, 2017). "On contrast TLR2−/− mice display decreased the severity of giardiasis through enhanced proinflammatory cytokines production." (PMID 28979269, 2017). "Importantly, studies have revealed the functions and mechanisms associated with the innate immune responses mediated by TLR2 and TLR4 during Giardia infection." (PMID 34336841, 2021). "Our study demonstrated that G. lamblia induced a decreased production of proinflammatory cytokines by activating AKT signal pathway via TLR2 in vitro and which might result in severity giardiasis in vivo." (PMID 28979269, 2017). "The role of host TLR2–AKT signal pathway on controlling giardiasis was elucidated." (PMID 28979269, 2017). "However, the role of host TLR2 as an inflammatory response on controlling the severity of giardiasis remains poorly understood." (PMID 28979269, 2017). "In summary, a new role for host TLR2 in controlling giardiasis severity has been identified." (PMID 28979269, 2017). "It was reported that Giardia infection can enhance the production of proinflammatory cytokines, such as TNF-α, IFN-γ, IL-6, and IL-12 p40 in PMs, through the TLR2-mediated activation of MAPK signaling." (PMID 34943932, 2021). "Both TLR2−/− and AKT-blocked mice showed significantly less parasite burden and shorter persistence than WT mice during Giardia infection." (PMID 28979269, 2017). "Both TLR2−/− and AKT-blocked mice presented with significantly higher weight gain rate than WT mice during Giardia infection." (PMID 28979269, 2017). "This study demonstrated that GEVs could be internalized into primary mouse peritoneal macrophages, regulate host cell innate immunity via TLR2 and NLRP3 inflammasome signaling pathways, and may provide new targets against giardiasis." (PMID 33798196, 2021). "In this study, we investigated the role of TLR2 as a non-protective inflammatory response on controlling the severity of giardiasis." (PMID 28979269, 2017). "Yet, unlike TLR4, TLR2 served as an apoptosis promoter during Giardia infections." (PMID 36937289, 2023). "In addition, macrophages from TLR2−/− mice in vitro showed enhanced production of IL-12 p40, TNF-α, and IL-6 but not IFN-γ, while TLR2−/− mice only showed enhanced production of IL-12 p40 and IFN-γ in vivo in response to Giardia infection." (PMID 28979269, 2017). "One possible explanation for this discrepancy could be that macrophages are not the only TLR2-expressing cells involved during Giardia infection in vivo." (PMID 28979269, 2017).
Giardia infection (continued). "We found that TLR2−/− mice did not affect TNF-α and IL-6 production in vivo, while AKT-blocked mice did increase the production of these two cytokines during Giardia infection." (PMID 28979269, 2017).
Hepatic steatosis (8 papers, 2012 to 2025). Steatosis is a term used to denote lipid accumulation within hepatocytes. "In HFD-induced mice, TLR2 deficiency reduces hepatic steatosis." (PMID 27446858, 2016). "However, hepatic steatosis has been reported to be independent of TLR2 signaling." (PMID 27446858, 2016).
Lewis lung carcinoma (8 papers, 2009 to 2021). "For example, Lewis lung carcinoma (LLC) cells secrete factors which activate TLR2 in murine macrophages, mediating IL-6 and TNFα production and inducing lung inflammation." (PMID 33922955, 2021). "Extracellular matrix protein versican derived from Lewis lung carcinoma was found to activate bone marrow-derived macrophages by binding to TLR2, leading to secretion of inflammatory cytokines such as TNF-α to promote metastasis." (PMID 32382015, 2020). "A change of CD11b+Gr1+bone marrow derived suppressor cells probably pre-granulocytes were believed to be responsible for the reduced metastasis of Lewis lung carcinoma cells in TLR2−/− mice." (PMID 19668347, 2009). "Studies have also shown that tumor cell secreted factors enhance Lewis lung carcinoma metastasis through their effects on Toll-like receptor 2 signaling in host bone marrow derived cells (BMDCs), including myeloid cells." (PMID 19668347, 2009). "Lewis lung carcinoma (LLC) activated macrophage to produce IL-6 and TNF-а through activation of TLR2 and TLR6." (PMID 27336891, 2016). "By activating TLR2:TLR6 complexes and inducing TNF-α secretion in myeloid cells, versican strongly enhances Lewis lung carcinoma metastatic growth." (PMID 20145615, 2010).
liver cancer (8 papers, 2012 to 2025). An epithelial or non-epithelial malignant neoplasm that arises from the liver. "TLR2 loss has been shown to impair immune- and senescence-related tumor suppressor effects in carcinogen-induced models of liver cancer, but, to date, the role of TLR2 in lung tumor progression and human disease in particular has not been investigated." (PMID 36351380, 2022). "Interestingly, this study pointed out that the distribution of TLR2-196 to -174 del/ins alleles in HCV infected patients without liver cancer and healthy control was identical." (PMID 30112356, 2018). "The accumulation of secondary bile acids in the livers of HFD mice suppresses anti-tumor immunity through a PTGER4 receptor on CD8 cells, which is mediated by the Toll-like receptor 2 (TLR2) signaling pathway, thereby contributing to liver cancer progression." (PMID 31231615, 2019). "Thus, findings indicated that TLR2 del/del genotype condition correlate with primary liver cancer rather than HCV-positive malignant lymphoproliferation." (PMID 27183918, 2016).
lymphoma (8 papers, 2016 to 2024). A malignant (clonal) proliferation of B- lymphocytes or T- lymphocytes which involves the lymph nodes, bone marrow and/or extranodal sites. "Accordingly, activating TLR2 signaling in the murine EG7 lymphoma model via the Pam2CSK4 lipopeptide, leads to an increased immunosuppressive activity of MO-MDSCs as they further differentiate into protumoral macrophages." (PMID 30349530, 2018). "Primary lymphoma cells from a MCL case showed detectable levels of TLR2 and, more markedly, of TLR5 as compared to those of purified normal B lymphocytes." (PMID 27123851, 2016). "Similarly, neutrophils harvested from lymphoma patients 3 days after initiation of treatment with ibrutinib or acalabrutinib displayed defective TLR2-, FcγR-, and Dectin-1-mediated ROS production relative to their preBTKi treatment baseline." (PMID 38696257, 2024). "TLR expression was highly variable among lymphoma subtypes; for example, TLR5 showed lower expression in follicular lymphoma, and TLR2 was overexpressed in both diffuse large B-cell lymphoma and peripheral T-cell lymphoma." (PMID 35715478, 2022). "When a TLR2-agonist, lipoprotein Pam2CSK4, is administered intravenously, TLR2-expressing PMN-MDSCs accumulate and proliferate systemically in EG7 lymphoma-bearing mice." (PMID 32733461, 2020).
mucositis (8 papers, 2015 to 2024). Mucositis is inflammation and damage of the mucous membranes lining the mouth and other parts of the gastrointestinal (GI) tract. "The protective role of MyD88 and TLR2 and TLR9 in irinotecan-induced mucositis was associated with a pronounced reduction of the local inflammatory reaction, as detected by the measurement of myeloperoxidase activity and COX–2 and IL–1β production." (PMID 26440613, 2015). "Pectin also blocks TLR2-dependent inflammation and can prevent mucositis through this mechanism." (PMID 39080025, 2024). "In addition to TLR2 and 4, other TLRs have also been explored in the context of mucositis, largely TLR5 and 9, although results are sporadic and somewhat heterogeneous." (PMID 39080025, 2024). "Interestingly, Frank and colleagues showed that TLR2 knockout mice injected with methotrexate present an exacerbated mucositis." (PMID 26440613, 2015). "Since TLR2 and IL‐6 are recognized to be crucial in the development of intestinal mucositis, future research should focus on testing whether wheat hydrolysates can be applied in clinical nutrition to attenuate mucositis." (PMID 30354027, 2018). "In addition, similar to the TLR2-/- and TLR9-/- mice, the mice with a genetic deletion of MyD88 were markedly protected from the development of mucositis, as indicated by a reduced production of inflammatory markers and intestinal damage." (PMID 26440613, 2015).